FGFR1 (fibroblast growth factor receptor 1)
Diseases named in the same sentence as FGFR1 in open-access papers (continued):
Sharing a sentence is not in itself a finding about the gene and the disease.
lung carcinoma (continued). "Similar association between FGFR1, FGFR3, FGFR4 and brachyury gene expression was also observed in lung cancer cell lines." (PMID 27893433, 2016). "Elucidation of this mechanism offers opportunities for application of novel chemotherapeutic strategies against lung cancer that target FGFR1/MAPK/brachyury pathway." (PMID 27893433, 2016). "Most importantly, genetic alternation of the FGFR1 led to epithelial malignancies in oral squamous, esophageal squamous, bladder, ovarian, and lung cancer." (PMID 26788508, 2015). "Elevated levels of FGFR1 have been found in a number of human cancers, including prostate cancer, lung cancer, gastric cancer, and so on." (PMID 25760077, 2015). "Although a variety of ATP-competitive FGFR1 inhibitors with therapeutic prospects for lung cancer have been identified, most of them failed in pre-clinical or clinical studies because of their low efficacy or high toxicity." (PMID 25880284, 2015). "Fibroblast growth factor receptor 1 (FGFR1) is correlated closely with the occurrence and development of lung cancer." (PMID 25880284, 2015). "Accumulating evidence suggests that high expression of FGFR1 is closely related to the development of lung cancer especially in non-small cell lung cancers (NSCLC)." (PMID 24980830, 2014). "In our present study using lung cancer cell lines, FGFR1 is most abundant receptor of the four family proteins in afatinib-resistant clones of PC9, and there was no enhancement in expression of other FGFR family proteins FGFR2, FGFR3 and FGFR4." (PMID 25115383, 2014). "The high expression of FGFR1 is closely related to the development of lung cancer especially in NSCLC, and it plays a crucial role in tumor cell proliferation, angiogenesis, migration and survival)." (PMID 24980830, 2014). "Amplification of FGFR1 is already identified as a therapeutic target in lung cancer, but up to now the role of FGFR1 in mesothelioma is unclear." (PMID 25138167, 2014). "Here we have shown that FGFR1 is frequently amplified in lung carcinomas and that this amplification is enriched in lung SCCs." (PMID 21666749, 2011). "The Sanger group also found two other somatic mutations in genes that encode the related family members, FGFR1 and FGFR2, in lung cancer specimens." (PMID 17487277, 2007). "To comprehensively identify mutations mediating resistance to the FDA-approved inhibitors pemigatinib (designed to target FGFR1–3) and futibatinib (designed to target FGFR1–4), we established a second pooled high-throughput system in the FGFRi-sensitive lung cancer cell line NCI-H1581." (PMID 41361008, 2026). "Additionally, human lung cancer xenograft and patient-derived xenograft models with a mesenchymal phenotype and high FGFR1 expression were sensitive to the combination of G12C inhibitors and pemigatinib." (PMID 40788860, 2025). "In addition to the alterations in the EGFR, that, like the mutations of K-Ras, are predominantly found in adenocarcinoma, in other lung cancer entities, FGFR1 amplifications are identified frequently." (PMID 40806483, 2025). "In lung cancer cell lines with the FGF2/FGFR1 pathway, targeting this resistance mechanism with EGFR-specific TKI does not significantly increase apoptosis, indicating that FGFR inhibitors may stabilize tumor progression rather than cause tumor regression." (PMID 39544292, 2024). "A similar effect was observed in DMS114 lung cancer cells, also overproducing FGFR1." (PMID 39329123, 2024). "Indeed, SOX2 expression is stimulated by fibroblast growth factor receptor 1 (FGFR1) activation in lung cancer." (PMID 38612911, 2024). "Overexpression of FGFR1 has been reported in a variety of cancers, including carcinomas of lung, breast, oral cavity, the ovaries, urinary bladder and prostate, as well as mesenchymal or lymphoid malignancies such as rhabdomyosarcoma and acute myeloid leukemia." (PMID 37993879, 2023).
lung carcinoma (continued). "It is important to note that other relevant mutations typically associated with lung cancer (such as ALK, ROS1, RET, FGFR1, ERBB2, etc.)have been found with frequencies compatible with previously published data, but without a significant difference between subgroups." (PMID 37173325, 2023). "Thus, in 9 of 25 specimens of 8p-amplified lung cancer, we found tail-to-tail rearrangements close to the transcriptional start site of FGFR1." (PMID 37606995, 2023). "Tail-to-tail rearrangements close to the FGFR1 gene in primary human lung cancer." (PMID 37606995, 2023). "For example, FGFR1-amplified lung cancer cell lines exhibit increased FGFR1 protein expression compared to non-FGFR1-amplified cell lines and are sensitive to shRNA-mediated knockdown or pharmacological inhibition of FGFR1." (PMID 37130917, 2023). "BAG4, a protein transcribed from a gene at 8p11.23 with a role in the inhibition of apoptosis, has been shown to transform breast cells and may have functional implications for lung cancer, being commonly coamplified with FGFR1 and NSD3." (PMID 36902501, 2023). "8p11 co-amplifies FGFR1 and 4EBP1 genes in breast and lung cancer." (PMID 35626002, 2022). "Functional studies revealed that silencing of FGFR1 strongly reduced the viability of the FGFR1-amplified lung cancer cells, inhibited cancer cell growth and clonogenicity, while application of the FGFR inhibitor revealed growth inhibition (p=0.0002) and induced apoptosis (p=0.008)." (PMID 35402233, 2022). "In this study we performed a wide-scale phosphoproteomic mass-spectrometry analysis to explore signaling pathways that lead to resistance toward FGFR1 inhibition in lung cancer cells that display (i) intrinsic, (ii) pharmacologically induced and (iii) mutationally induced resistance." (PMID 35853934, 2022). "Collectively, our phosphoproteomic analysis of lung-cancer cells resistant to FGFR1 inhibitor provides a large data library of resistance-associated phosphorylation patterns and leads to the proposal of a common resistance pathway comprising CD44, PAK1 and AKT activation." (PMID 35853934, 2022). "Several gatekeeper mutations in the FGFR family have been reported in preclinical studies in several cancer models, including FGFR1 V561M in lung cancer, FGFR2 V565I/N550K/V564F in endometrial cancer and cholangiocarcinoma, FGFR3 V555M in myeloma and FGFR4 V550L/V550E in rhabdomyosarcoma." (PMID 34068816, 2021). "Together, these results demonstrated that the overexpression of FGFR1 in lung cancer cells may contribute to resistance to KRASG12C inhibitors." (PMID 34858498, 2021). "However, several phase II clinical trials found its limited activity in FGFR1‐amplified lung cancer patients with an acceptable safety profile." (PMID 33655556, 2021). "Furthermore, T-Fc-vcMMAE displays high cytotoxicity to FGFR1-producing cells, including lung cancer cells with EC50 in the nanomolar range." (PMID 33962559, 2021). "Moreover, it has been suggested that high expression of both FGFR1 and SOX2 is associated with shorter survival of lung cancer patients." (PMID 34830951, 2021). "Adachi and co-workers identified a role for other receptor tyrosine kinases such as EGFR, PDGFRα (platelet-derived growth factor receptor α), and IGFR (insulin-like growth factor receptor) in the emergence of resistance to FGFR inhibitor treatment in FGFR1-amplified lung cancer." (PMID 34830951, 2021). "These FGFR1-amplified lung cancer cells showed primary resistance to the FGFR inhibitors AZD4547 or erdafitinib and were characterized by sustained MAPK pathway activation from constitutive MET and RAS activation, as well as deletion of DUSP6, a negative regulator of MAPK signaling." (PMID 34638374, 2021). "Lung cancer cell lines with FGFR1 amplification were highly sensitive to FGFR inhibitors." (PMID 34638374, 2021). "Interestingly, FGFR1 also mediates adaptive resistance to MEK inhibitors in KRAS-mutant lung cancer cells." (PMID 34858498, 2021).
lung carcinoma (continued). "FGFR1‐amplified lung cancer models respond to FGFR inhibitors in preclinical studies in both non‐small cell lung cancer (NSCLC) and small‐cell lung cancer (SCLC), especially in SqCLC, with 9.3% in stage I, 22% in stage II, and 19% in stage IV with brain metastasis." (PMID 33655556, 2021). "This study reports a synergistic drug combination by targeting FGFR1 and PLK1 and identifies autophagy as a protective mechanism that limits the efficacy of FGFR1/PLK1 inhibitor therapy in KRAS‐mutant lung cancer, suggesting a novel strategy to treat the daunting disease." (PMID 34369083, 2021). "Over the last decade, FGFR1 has emerged as a key inducer of ciliogenesis in the embryonic tissues of lower organisms, including the zebrafish, xenopus, and chick, as well as in human lung carcinoma and rhabdomyosarcoma cells." (PMID 34705506, 2021). "Although FGFR gatekeeper mutations have not been identified in lung cancer patients yet, in vitro binding assays have shown that the gatekeeper residue V561M in FGFR1 is a mechanism of acquired resistance to FGFR inhibitors." (PMID 34068816, 2021). "Key findings: CCND1 was co-overexpressed with FGFR1 in lung cancer patients." (PMID 32380883, 2020). "Cell/molecular biological and analytical chemistry methods were applied to investigate uptake kinetics/subcellular distribution, the role of lipid droplets (LDs) and lipoid microenvironment compartments in responsiveness of FGFR1‐driven lung cancer cells toward ponatinib." (PMID 32064608, 2020). "FGFR1 theoretically may be a promising potential target in SCLC, yet it is curious that FGFR1-amplified lung cancer patients experienced limited benefit from FGFR inhibition." (PMID 32626515, 2020). "Despite current studies pointing to the fact that CCND1 is overexpressed and activated in a variety of cancers, few reports discuss the underlying molecular mechanisms by which CCND1 is regulated or activated in malignant tumors, especially in FGFR1 amplified lung cancer." (PMID 32380883, 2020). "Therefore, we, for the first time, proposed that existence of miR-214-3p-FGFR1-Wnt/MAPK/PI3K-AKT axis in FGFR1-amplified lung cancer." (PMID 31492847, 2019). "Co-targeting miR-214-3p and FGFR1 could provide greater benefits to patients with FGFR1-amplified lung cancer." (PMID 31492847, 2019). "The reason for the disparate results between lung and endometrial cancer models is unknown but could be due to higher expression of Mcl‐1 in lung cancers and/or differences in other prosurvival/pro‐apoptotic proteins regulated by FGFR1 and FGFR2." (PMID 30537101, 2019). "Therefore, as a promising target in LSQCC and SLCL, there is an urgent need to further explore the development and progression of FGFR1 in FGFR1-amplified lung cancer." (PMID 31492847, 2019). "Thus, EGFRL858R/T790M/FGFR1 dual inhibitor 15c can be developed as an ideal candidate drug for FGFR1-amplified EGFR-TKIs resistant lung cancers." (PMID 31998131, 2019). "scFvD2-Fc-MMAE displays cytotoxic activity against lung cancer cells with FGFR1 overproduction." (PMID 30577533, 2018). "Importantly, treatment of lung cancer cell lines bearing FGFR1 amplifications with FGFR inhibitors inhibits cell growth and survival." (PMID 30060526, 2018). "Unlike EGFR mutation in lung cancer, which is more prevalent in Asians than in Caucasians, the frequency of FGFR1 amplification in ESCC does not seem to be widely different by ethnicity." (PMID 29179482, 2017). "Whether FGFR1 contributes to the maintenance of stem cell-like phenotype of FGFR1-amplified lung cancer cells remains elusive." (PMID 26936993, 2016). "Moreover, msFGFR2c significantly inhibited the proliferation of FGFR1IIIc-positive NCI-H1299 lung cancer cells by the suppression of FGF-2-induced FGFR1 activation and suppressed the growth of NCI-H1299 transplanted tumors in nude mice." (PMID 28049184, 2016).
lung carcinoma (continued). "In addition, human lung cancer cells with higher brachyury expression were more sensitive to inhibitors targeting FGFR1/MAPK pathway." (PMID 27893433, 2016). "The FGFR1 gene is amplified in lung cancer at varying frequencies (depending on the histological subtype between 5.6% and 19% for SCLC and NSCLC SCC, respectively) and overexpression of FGFR1 was shown to be a driving oncogenic factor in subgroups across all lung cancer subtypes." (PMID 27367030, 2016). "In this study, treatment with FGFR1 inhibitor AZD4547 suppressed the growth of tumor spheres and reduced ALDH positive proportion in FGFR1-amplified lung cancer cells in vitro, as well as inhibited the growth of oncospheres and parental cells in xenograft models." (PMID 26936993, 2016). "Similar results were observed in lung cancer cells that harbor FGFR1 amplification." (PMID 27223434, 2016). "We also carried out in-depth analysis of the FGFR1 locus in a subset of lung cancer cell lines to determine whether the amplicon structure differs between pre-preclinical and clinical models." (PMID 26905262, 2016). "In addition, differences in the FGFR1 amplification rate between squamous cell carcinoma and adenocarcinomas has also been reported from cancers of the lungs." (PMID 26555375, 2015). "With regard to the predictive value for treatment in lung cancer, it also found that patients with FGFR1 amplification could benefit from adjuvant chemotherapy, but it cannot be validated in our analysis for lacking of more studies in lung cancer." (PMID 26788508, 2015). "Accumulating evidence suggests that high expression of FGFR1 is closely related to the development of lung cancer especially in non-small cell lung cancers (NSCLC), to which non-ATP competitive inhibitors represent an effective therapeutical approach due to their good specificity." (PMID 24980830, 2014). "FGFR1 represents a promising new target in lung cancer therapy." (PMID 23842453, 2013). "They concluded that FGFR-1 may represent a promising therapeutic target in non-small cell lung cancer and even better in the orphan subtype of lung carcinoma such as the squamous." (PMID 23270564, 2012). "Amplification or activation of FGFR1 has been reported in oral squamous carcinoma, esophageal squamous cell carcinomas, ovarian cancer, bladder cancer, prostate cancer, rhabodomyosarcoma, and lung cancer." (PMID 21666749, 2011). "suggesting that FGF18 may affect lung cancer progression through the FGFR1 pathway." (PMID 37228502, 2023). "Moreover, combination between AKT and FGFR1 inhibitors may pave the way for an effective therapy of patients with treatment-resistant FGFR1-dependent lung cancer." (PMID 35853934, 2022). "In addition, given to the previous result that FGFR1 is elevated in lung cancer." (PMID 32380883, 2020). "In addition, potential targetable amplifications were detected, i.e. high level amplifications of ERBB2 (colorectal carcinoma, salivary duct carcinoma, prostate cancer, ovarian cancer), MET (lung cancer, esophageal carcinoma), and FGFR1 (lung cancer, colorectal carcinoma)." (PMID 32264863, 2020). "However, the regulatory mechanism between miRNAs and FGFR1 in lung cancer remains unclear and extremely critical." (PMID 31492847, 2019). "Therefore, it is necessary to explore the regulatory mechanism between miRNAs and FGFR1 in FGFR1-amplified lung cancer, which may help explain the modest suppression of lung cancer by FGFR1 inhibitors, and, more importantly, develop novel and better therapies." (PMID 31492847, 2019). "In addition to oncogenic EGFR and distinct RTKs activated through gene-rearrangements, increased expression of the non-mutated RTK, FGFR1, is observed in lung cancers of all histologies, mesotheliomas and HNSCC." (PMID 29458371, 2018). "Importantly, a fraction of FGFR1 were identified in the mitochondria of lung cancer cells." (PMID 30577533, 2018).
lung carcinoma (continued). "Furthermore, our findings indicate that clinical efficacy of treatments for FGFR1-driven lung cancer may be achieved by combining autophagy inhibitors and FGFR-specific TKIs." (PMID 28558758, 2017). "We reported that in afatinib-resistant sublines derived from the lung cancer cell line PC9 that harbors an activating EGFR mutation, the levels of multiple EGFR family proteins are markedly reduced and accompanied by compensatory activation of an FGF2/FGFR1 autocrine signaling pathway." (PMID 29050315, 2017). "Therefore, targeted inhibition of FGFR1 signaling molecules may inhibit tumor progression in a subset of brachyury-driven lung cancer." (PMID 27893433, 2016). "Studies have indicated that FGF9 activates FAK, AKT and ERK signalling through FGFR1, inducing EMT to stimulate tumourigenesis and hepatic metastasis in Lewis lung carcinoma cells." (PMID 39001509, 2024). "AZD4547 is a FGFR1 inhibitor that markedly suppressed SOX2 expression and tumor growth in orthotopic and subcutaneous H1581 and DMS1144 lung cancer xenograft models." (PMID 38612911, 2024). "Some of the RTKs that were highly expressed in lung cancer cell lines are the Epidermal growth factor receptor (EGFR), fibroblast growth factor receptor 1 (FGFR1), insulin-like growth factor 1 receptor (IGF1R), and tyrosine-protein kinase Met (MET)." (PMID 36926328, 2023). "FGFR1 activation is a known driver in various malignant diseases such as breast, prostate, myeloproliferative neoplasms, AML, ALL, CML, glioblastoma, and lung cancer." (PMID 37598282, 2023). "FGFR1 is considered to be a driver lesion in LSCC and even a potential biomarker for treatment of lung cancer." (PMID 37445817, 2023). "In summary, tail-to-tail rearrangements upstream of FGFR1 and presumably destructive rearrangements in NSD3 can be frequently observed in lung cancer cell lines, PDXs, and primary squamous cell lung carcinomas." (PMID 37606995, 2023). "In the previous work, we have shown that FGF1 can protect lung cancer (DMS114) and osteosarcoma (U2OSR1) cells, which overexpress FGFR1, from drugs targeting tubulin polymerization." (PMID 37509496, 2023). "In summary, our study establishes the translational targets of 4EBP1 and the therapeutic advantage of FGFR1 and PI3K inhibitors in 4EBP1-amplified breast and lung cancer." (PMID 35626002, 2022). "Activation of FGFR1 was reported to initiate EMT in several cancer types, including primary or secondary drug resistant lung cancer and lung cancer cell lines such as H1581." (PMID 35955773, 2022). "In KRASG12C-mutant lung cancers, a synergistic effect was observed in the dual inhibition of MEK and FGFR1." (PMID 35053550, 2022). "Among the known driver CNVs found in lung cancer sample, the copy number of MYC and FGFR1 increased in the resistant time point." (PMID 35402275, 2022). "In FGFR1-amplified lung cancer cell lines, MET-amplification is a mechanism of resistance to FGFR-targeting drugs and conversely, FGFR1-dependent resistance to MET inhibitors is observed in leukaemia, kidney and prostate cancers." (PMID 33772015, 2021). "For example, an interaction between FGFR1 and EGFR can marginally increase epidermal growth factor (EGF)-mediated AKT and STAT3 signaling outputs in lung cancer cells." (PMID 34068954, 2021). "Currently, multiple clinical studies are in progress in patients with FGFR1 aberrantly activated cancers, including SCLL, breast, prostate, and lung cancer." (PMID 34114373, 2021). "Internalization into NCI-H520 cells, previously characterized as lung cancer cells with increased levels of FGFR1 expression, was compared to internalization into HCC-95 lung cancer cells with low levels of FGFR1." (PMID 34867353, 2021). "In afatinib-resistant lung cancer cell line, among EMT-related markers, only knockdown of Twist resulted in a complete downregulation of FGFR1, with concomitant inhibition of AKT and ERKs phosphorylation, which re-sensitized cells to afatinib." (PMID 34830951, 2021).